CLN3 (CLN3 lysosomal/endosomal transmembrane protein, battenin)
Diseases named in the same sentence as CLN3 in open-access papers (continued):
Sharing a sentence is not in itself a finding about the gene and the disease.
Parkinson's (2 papers, 2016 to 2020). "Abnormal protein trafficking and membrane dynamics are a hallmark in many neurodegenerative diseases such as Parkinson's, Alzheimer's, Huntington's disease, as well as CLN3 disease." (PMID 31655107, 2020). "Similarly to PEP4, overexpression of YPK9 was observed to reduce the accumulation of α-synuclein, a notable pathology in Parkinson's disease (PD) and also observed in CLN3 disease models." (PMID 31655107, 2020).
retinal disease (2 papers, 2017 to 2022). "This suggests an important role of CLN3 in outer retinal homeostasis, and recently the retinal pigment epithelium (RPE) cells, that both act as a selective barrier to and a vegetative regulator of the photoreceptor layer, have been designated as key targets in CLN3 retinal disease propagation." (PMID 36438942, 2022).
autosomal recessive retinitis pigmentosa (1 paper, 2024). Autosomal recessive retinitis pigmentosa (RP) is an autosomally recessive inherited retinal dystrophy leading to progressive loss of the photoreceptors and retinal pigment epithelium and resulting in blindness usually after several decades. "Invitae reported that this had a pathogenic deletion in CLN3, which is associated with autosomal recessive retinitis pigmentosa; BG also reported this CLN3 allele as pathogenic." (PMID 38892829, 2024).
Bradycardia (1 paper, 2022). A slower than normal heart rate (in adults, slower than 60 beats per minute). "In 2014, two siblings with a specific, not previous described CLN3 mutation both received a pacemaker due to severe bradycardia and sick sinus syndrome." (PMID 35356463, 2022).
breast adenocarcinoma (1 paper, 2015). "CLN3 expression levels were analyzed by comparing malignant tissue from breast adenocarcinomas to corresponding non-tumor tissue." (PMID 26528430, 2015).
cardiac arrhythmia (1 paper, 2025). Any disturbances of the normal rhythmic beating of the heart or MYOCARDIAL CONTRACTION. "In addition to GI symptoms, CLN3 disease manifestations include cardiac arrhythmia, autonomic dysfunction and peripheral sensory abnormalities, clumsiness, slow or dysregulated movements, and subsequent loss of ambulation and muscular atrophy." (PMID 41430350, 2025).
Charcot-Marie-Tooth type 2 neuropathies (1 paper, 2025). "Stress granules have recently been implicated in Charcot-Marie-Tooth type 2 neuropathies and most pertinently CLN3 putative interactors." (PMID 41173878, 2025).
Crohn disease (1 paper, 2024). A gastrointestinal disorder characterized by chronic inflammation involving all layers of the intestinal wall, noncaseating granulomas affecting the intestinal wall and regional lymph nodes, and transmural fibrosis. "Some of these traits (i.e., platelet-to-lymphocyte ratio, general cognitive ability) as well as Crohn’s disease are further linked to JIA through the neighbouring cluster 6 genes (HLA-FAS1, BAK1, CLN3, SGF29)." (PMID 39175752, 2024).
developmental delay (1 paper, 2014). "Human genetic studies indicated that copy number variants (duplications and deletions) including CLN3, and possibly another gene in the CISD2/PPT1/CLN3 network, are over-represented in individuals with developmental delay." (PMID 24705017, 2014).
Dysarthria (1 paper, 2025). Dysarthric speech is a general description referring to a neurological speech disorder characterized by poor articulation. "13/15 (87%) assessed participants with CLN3 disease had dysarthria, including moderate to severe neurogenic stuttering in 5/15 (33%)." (PMID 39821609, 2025). "In CLN3 disease, neurogenic stuttering was a core manifestation of dysarthria, with onset in the first decade of life, considerably earlier than fine and gross motor impairments develop." (PMID 39821609, 2025).
hepatocellular carcinoma (1 paper, 2021). A malignant tumor that arises from hepatocytes. "Steroid lipofuscosis 3 (CLN3) is abnormally expressed in hepatocellular carcinoma and can promote tumor progression and metastasis." (PMID 34257653, 2021).
Joubert syndrome 3 (1 paper, 2021). Any Joubert syndrome in which the cause of the disease is a mutation in the AHI1 gene. "CLN3 and AHI1 typically cause JNCL 3 and Joubert syndrome 3, respectively; however, probands of families IRD16 and IRD49 showed typical RP phenotypes, without any additional syndromic manifestations of either disease, at least for their current age." (PMID 33921607, 2021).
language disorder (1 paper, 2025). A category of disorders characterized by an impairment in the development of an individual's language capabilities, which is in contrast to his/her non-verbal intellect. "Whilst speech and language disorders are well established presenting features in CLN2 disease, they are also important in CLN3 disease." (PMID 39821609, 2025).
liver cancer (1 paper, 2023). An epithelial or non-epithelial malignant neoplasm that arises from the liver. "More importantly, our study revealed for the first time that CLN3, GBA, and LAPTM4B are specifically expressed in hepatocytes in the liver and promote the progression of liver cancer through multiple tumor-related pathways." (PMID 38114725, 2023). "Understanding the molecular mechanisms of CLN3, GBA, and LAPTM4B in liver cancer cells may help to develop new therapeutic targets for liver cancer." (PMID 38114725, 2023). "Of note, CLN3, GBA, and LAPTM4B were specially expressed in Hepatocytes, which may be novel biomarkers for liver cancer Hepatocytes." (PMID 38114725, 2023). "Therefore, CLN3, GBA, and LAPTM4B may be involved in cancer progression of liver cancer hepatocytes." (PMID 38114725, 2023).
melanoma (1 paper, 2017). A malignant, usually aggressive tumor composed of atypical, neoplastic melanocytes. "Interestingly, the top two upregulated genes in melanomas from RHC were PRKAA1 (fold change=1.37, p=0.08) and PIK3C3 (fold change=1.23, p=0.09) while the top two downregulated were YWHAG (fold change=0.62, p=0.29) and CLN3 (fold change=0.77, p=0.3)." (PMID 28030792, 2017).
myoclonic epilepsy (1 paper, 2023). A group of epilepsy syndromes in which myoclonic seizures are a prominent feature. "Previously, classic CLN3 disease was sometimes loosely considered along with CLN2 and CLN6 to have a progressive myoclonic epilepsy phenotype." (PMID 37039534, 2023).
neuronal ceroid lipofuscinosis type 2 (1 paper, 2021). "However, one specific protein detected in both human and mouse CSF, namely CALB2, was significantly elevated in both the proteomics analysis and was confirmed by ELISA, similar to that observed in late infantile neuronal ceroid lipofuscinosis type 2 (CLN2) and CLN3 patients." (PMID 33478506, 2021).
ovarian carcinoma (1 paper, 2021). A malignant neoplasm originating from the surface ovarian epithelium. "It has been proved that CLN3 is abnormally highly expressed in a variety of cancer-related cell lines, including ovarian cancer." (PMID 33763357, 2021). "Further studies have shown that CLN3 plays an important role in tumorigenesis and drug resistance of ovarian cancer." (PMID 33763357, 2021).
protein deficiencies (1 paper, 2022). "Recent experimental ocular gene therapies on animal models with soluble lysosomal enzyme deficiencies (CLN1, CLN5, CLN10, and CLN11) and transmembrane protein deficiencies (CLN3 and CLN6) have shown the strong potential of gene therapeutic approaches to effectively treat NCL-related retinopathies." (PMID 35509995, 2022).
retinitis pigmentosa (1 paper, 2019). Retinitis pigmentosa (RP) is an inherited retinal dystrophy leading to progressive loss of the photoreceptors and retinal pigment epithelium and resulting in blindness usually after several decades. "Representation of reported disease‐causing mutations, their associated regions of the DNA (i.e. promoter, coding, noncoding), cDNA change, genomic DNA change, protein change, type of mutation, human phenotype (CLN3 disease or nonsyndromic retinitis pigmentosa)." (PMID 31568712, 2019).
speech disorder (1 paper, 2025). A term referring to disorders characterized by the disruption of normal speech. "Six participants (6/17, 35%) with CLN3 disease had delayed speech and language milestones and an additional two participants (2/17, 12%) had speech disorders prior to diagnosis." (PMID 39821609, 2025).
teratocarcinoma (1 paper, 2015). A germ cell tumor characterized by the presence of an embryonal carcinoma component and a teratoma component. "Previous work had shown that CLN3 negatively modulates ceramide generation in NT2 cells that are human teratocarcinoma-derived progenitor cells." (PMID 26528430, 2015).
neurodegenerative disease (17 papers, 2004 to 2026). A disorder of the central nervous system characterized by gradual and progressive loss of neural tissue and neurologic function. "CLN3 disease, caused by biallelic mutations in the CLN3 gene, is a rare pediatric neurodegenerative disease that has no cure or disease modifying treatment." (PMID 37035740, 2023). "JNCL is a recessively inherited, childhood-onset neurodegenerative disease most-commonly caused by a ~1 kb CLN3 mutation." (PMID 15588329, 2004). "In the proteomic study of CSF from children with the syndromic CLN3-Batten, a fatal neurodegenerative disease caused by mutations in the endolysosomal transmembrane CLN3 protein, a protein implicated in axonal development, were identified as candidate biomarkers." (PMID 38136601, 2023). "Although, our study shows only limited beneficial effects of acidified drinking water on the neuropathology and neurological function in Cln3−/− mice, any improvement is appreciated in the case of a fatal neurodegenerative disease." (PMID 31628420, 2019). "Together, these data establish JNCL neurodegenerative disease hallmarks and a functional decline that is ongoing in aging homozygous Cln3Δex7/8 mice, confirming the usefulness of this accurate genetic model for JNCL research." (PMID 22701626, 2012). "For this, Cln3 protein can be a possible target for ML extract in D. discoideum cells, where a neuroprotective role has been noted for M. oleifera, and it has been highlighted as a potential form of treatment for neurodegenerative diseases." (PMID 40136540, 2025). "With a growing interest in SG-modulating drugs for the treatment of neurodegenerative diseases, novel insights into the molecular basis of CLN3 Batten disease may reveal avenues for disease-modifying treatments for this debilitating childhood disease." (PMID 36965618, 2023). "Importantly however, a link between CLN3 and Tor signalling specifically, as reported here, is a novel mechanistic and therapeutic insight into CLN3 disease, the most common paediatric neurodegenerative disease." (PMID 28357272, 2015).
cancer (12 papers, 2012 to 2024). A tumor composed of atypical neoplastic, often pleomorphic cells that invade other tissues. "Thirty-seven significantly associated cancer–gene pairs and four genes (GBA1, SGSH, HEXA, and CLN3) with a Pan-Cancer association were identified (Pan-Cancer is a cohort of 2567 patients with cancer)." (PMID 39404425, 2024). "Increased cancer prevalence has also been reported in carriers of a potentially pathogenic variant of an LSD gene, namely CLN3, SGSH, GUSB, NEU1, and, to a lesser extent, in other genes." (PMID 39404425, 2024). "When CLN3 was suppressed, carcinoma cell lines experienced a notable decrease, which was also confirmed in human tumor xenografts in mice." (PMID 39000458, 2024). "Previous work has shown that CLN3 is anti-apoptotic, and that diminishing levels of CLN3 protein in cancer cells enhances ceramide production and results in death of cancer cells." (PMID 26528430, 2015). "The mammalian homolog of Cln3, Cyclin D1, is an important regulator of the G1/S progression in normal cells and commonly deregulated in cancer." (PMID 23217712, 2012). "The expression and function of CLN3 may serve as predictive markers of patient prognoses in the mentioned cancers and also serve as therapeutic targets." (PMID 39000458, 2024). "CLN3 may be a novel molecular target for cancer drug discovery with the goal of modulation of ceramide pathways." (PMID 26528430, 2015). "CLN3 expression may be an additional useful biomarker and a novel molecular target for cancer drug discovery, the latter achieved via modulation of ceramide pathways." (PMID 26528430, 2015). "Thus, the CLN3 protein is involved in the regulation of cancer cell growth." (PMID 39404425, 2024). "Moreover, blocking CLN3 expression using anti-sense strategies led to cancer-cell killing, suggesting CLN3p may be a potential therapeutic target." (PMID 26528430, 2015). "Due to the vital role played by lysosomes in cancer, a LRRS signature was constructed, including 8 genes, namely, CLN3, GBA, CTSA, BSG, APLN, SORT1, ANXA2, and LAPTM4B." (PMID 38114725, 2023). "Blocking CLN3 expression inhibited growth and viability of MCF7 cancer cells, and increased apoptosis as shown by PI staining." (PMID 26528430, 2015). "Using our extensive pan-cancer NK cell atlas, we were able to generate a solely NK cell-derived, tissue-residency signature (atlas-TR: PSMA2, SLC5A3, CCL4L2, CLN3, SCGB1A1, AREG), which outperformed the conventional literature-derived TR signature across tissue and tumor type." (PMID 38956379, 2024). "The four ARGs RHEB, NPC1, PRK3D, and CLN3 have not been reported in previous studies on HCC or other cancers." (PMID 37370041, 2023). "The genes ITGA3, HSPA8, CTSD, ATG12, CLN3, ATG7, and MAP1LC3C negatively influenced patient survival, whereas WIPI1 may protect the patients from cancer-related death." (PMID 35186475, 2022). "Using the Pan-Cancer TCGA dataset gathering RNA-seq data from 11,060 patients, an anticorrelation between TET2 expression and mRNA levels of lysosome proteins was confirmed for CLN3, CTSD, CTSF, CTSZ, IFI30, and NAGLU, suggesting TET2 might down-regulate lysosomal genes in various types of cancer." (PMID 35351824, 2022).
neurological diseases (8 papers, 2009 to 2025). "We have previously shown that a splice-switching antisense oligonucleotide (ASO) delivered to the central nervous system can reduce neurological disease burden in mouse models of CLN3 disease." (PMID 41189054, 2025). "Further, many unique genetic interactions of btn1102–208del correspond to conserved human orthologues, including genes related to eye and neurological diseases, for example, npc2 (Niemann–Pick C disease), linking these diseases with the pathogenesis of CLN3 disease." (PMID 33737578, 2021).
tumor (8 papers, 2006 to 2024). "An experimental study demonstrated that NEU1 siRNA can significantly suppress proliferation, apoptosis, and invasion of tumor cells by targeting lysosomal membrane proteins (CLN3 and CLN5)." (PMID 34513919, 2021). "When comparing IDC breast samples to non-tumor tissue from reduction mammoplasty patients, overexpression of CLN3 was most prevalent for IDC grades I and II (54%), and 50% in DCIS and also 50% in IDC grade III." (PMID 26528430, 2015). "There is an increase in percentages of CLN3 overexpression when tumor tissue is compared to tissue from reduction mammoplasties as opposed to normal tissue from the same patient removed at surgery." (PMID 26528430, 2015). "CLN3 has a copy number gain encompassing the VEGFA locus, found in 3% of the cases and linked to higher tumor grade and vascular invasion and being an aggressive subgroup." (PMID 24943349, 2014). "Hence, it is possible that CLN3 may also be overexpressed in non-tumor tissue surrounding the tumor." (PMID 26528430, 2015). "When comparing FFPE IDC breast samples to the corresponding non-tumor tissue, 38% of the DCIS cases showed overexpression of the CLN3 gene." (PMID 26528430, 2015). "Tumor status induced a significant increase in the expression of CerS2 (p < 0.0001), CerS6 (p < 0.0001), DEGS2 (p < 0.0001), SMPD1 (p < 0.05), and CLN3 (p < 0.0001); and a significant decrease in the expression of UGT8 (p < 0.0001) compared with expression in the corresponding non-tumor tissue." (PMID 26528430, 2015). "When comparing cancerous tissue to non-tumor tissue from reduction mammoplasties, no positive correlation was observed with respect to CLN3 overexpression and higher tumor grades, age, and menopause status." (PMID 26528430, 2015). "Discrepancy between CLN3 mRNA expression in non-tumor tissue surrounding the tumor and non-tumor tissue from reduction mammoplasties was calculated using the concordance correlation coefficient." (PMID 26528430, 2015). "Furthermore, of the six clinicopathological parameters studied (tumor grade, age, menopause status, ER, PR, and HER2), CLN3 overexpression was significantly associated with absence of HER2 expression (p = 0.045) in patients with IDC of the breast." (PMID 26528430, 2015). "The relative overexpression of CLN3 mRNA transcripts in IDC breast FFPE and fresh tissues was significantly higher than in surrounding control non-tumor tissues or in control non-tumor tissue from reduction mammoplasties." (PMID 26528430, 2015). "Of the clinicopathological characteristics of tumor grade, age, menopause status, estrogen receptor, progesterone receptor, and human epidermal growth factor receptor 2 (HER2), only absence of HER2 expression correlated with CLN3 overexpression." (PMID 26528430, 2015).
retinopathy (5 papers, 2014 to 2025). "For instance, ROs modeling CLN3-associated non-syndromic retinopathy revealed novel transcripts inducing faulty CLN3 synthesis, toxic substance accumulation, and morphological defects in photoreceptor progenitor cells." (PMID 39422807, 2025). "Genome-editing approaches using CRISPR/Cas9 have rescued the disease phenotype in iPSCs from patients with RP, XLRS, LCA4, LCA5, enhanced S-cone syndrome, or nonsyndromic retinopathy harboring CLN3 mutations, by revealing differentiation into ROs." (PMID 39422807, 2025). "In the present study, we demonstrate that knockdown of cln3 in zebrafish recapitulates several pathological features of the human disease including reduced survival, retinopathy, neurodegeneration, epileptiform activity and enlarged lysosomes with accumulation of subunit c." (PMID 27327661, 2016).
genetic disorder (4 papers, 2019 to 2022). "The genetic disorder, which is caused by recessive mutations affecting the CLN3 gene, features progressive vision loss, cognitive and motor decline and other psychiatric conditions, seizure episodes, leading to premature death." (PMID 31888773, 2019). "This is the first report of a CLN3‐associated genetic disorder in the Japanese population." (PMID 32441891, 2020). "CLN3 is a hereditary disease that affects the nervous system." (PMID 35139088, 2022).
neurodevelopmental disorder (4 papers, 2014 to 2026). A behavioral and cognitive disorder with onset during the developmental period that involves impaired or aberrant development of intellectual, motor, or social functions. "CLN3 disease, also known as juvenile Batten disease, is a recessively inherited neurodevelopmental disorder caused by mutations in the CLN3 gene." (PMID 41199165, 2025). "To examine this gene network specifically in neurodevelopmental disorders, we searched human genetic data for variants within CISD2, PPT1, CLN3 and the other 19 human genes identified by network analysis in humans." (PMID 24705017, 2014). "Our studies found that CNVs encompassing human CLN3 and SCAMP2 are associated with neurodevelopmental disorders." (PMID 24705017, 2014).
infection (3 papers, 2014 to 2024). The state of being infected such as from the introduction of a foreign agent such as serum, vaccine, antigenic substance or organism. "As Cdc42 is important for adhesion and fluid-phase endocytosis, Cln3−/− mice and JNCL patients may display BBB dysregulation when stressed, such as during an infection or as neurons succumb to disease." (PMID 24792215, 2014).